EPCAM (epithelial cell adhesion molecule)
Diseases named in the same sentence as EPCAM in open-access papers (continued):
Sharing a sentence is not in itself a finding about the gene and the disease.
Sepsis (2 papers, 2018 to 2020). Sepsis is defined as life-threatening organ dysfunction caused by a dysregulated host response to infection. "The MMP-7/EpCAM ratio differentiated NEC from sepsis and healthy controls with high diagnostic accuracy, although the study was limited by a small sample size and lack of information on how neonates were diagnosed for sepsis." (PMID 30094238, 2018). "The EVs expressed typical exosomal (CD63 and CD9) and epithelial (EpCAM) markers, which were further increased by sepsis." (PMID 33182773, 2020). "In conclusion, we have shown that gut-lavage EVs are exclusively IEC-derived and that their expression of an epithelial marker (EpCAM) is augmented by sepsis." (PMID 33182773, 2020).
T-cell leukemia (2 papers, 2014 to 2025). A malignant disease of the T-lymphocytes in the bone marrow, thymus, and/or blood. "To evaluate the binding specificity of magnetic nanoparticles to OC cells, we selected the EpCAM-high-expressing OVCAR3 cell line and the human T-cell leukemia cell line Jurkat as a negative control." (PMID 40792273, 2025).
teratocarcinoma (2 papers, 2013 to 2018). A germ cell tumor characterized by the presence of an embryonal carcinoma component and a teratoma component. "We show here that murine EpCAM (mEpCAM) is subject to regulated intramembrane proteolysis in various cells including embryonic stem cells and teratocarcinomas." (PMID 24009667, 2013). "The intensity of cleavage of EpCAM through BACE1 was cell line-dependent and appeared most prominent in HEK293 cells, whereas it was minor in teratocarcinoma cells, where major cleavage of EpEX was essentially metalloprotease-dependent." (PMID 24009667, 2013). "Interacting partners of full-length EpCAM were assessed using a combination of stable isotope labeling with amino acids in cell culture (SILAC), immunoprecipitation of YFP- and EpCAM-YFP in murine F9 teratocarcinoma cells, and identification of co-precipitated proteins by LC-MS/MS." (PMID 29379062, 2018).
urothelial cell carcinoma (2 papers, 2017 to 2020). "Previously we reported epithelial cell adhesion molecule (EpCAM) to be an antigen with high tumor distinctiveness for LN positive disease in urothelial cell carcinoma (UCC) of the bladder." (PMID 32942549, 2020). "The expression rates of EpCAM in urothelial cell carcinoma (UCC) of the bladder varies between 27% and 99% in different studies." (PMID 28820475, 2017).
uveal melanoma (2 papers, 2006 to 2025). A melanoma derived from melanocytes of the uveal tract. "We made an effort to detect EpCAM expression in 25 selected cases of uveal melanoma; however, none of them were positive, even in the UM epithelioid cell type." (PMID 17125516, 2006).
adenovirus infection (1 paper, 2020). "The mRNA level of EpCAM also elevated after adenovirus infection (data not shown)." (PMID 32843056, 2020).
alcoholic steatohepatitis (1 paper, 2019). "In a previous study, we reported on the first RNA sequencing-based transcriptome profiles of BECs isolated from alcoholic steatohepatitis patients through EpCAM- or TROP2-based FACS sorting (respectively epithelial cell adhesion molecule (TACSTD1) and trophoblast antigen 2 (TACSTD2)." (PMID 31547151, 2019).
alopecia (1 paper, 2022). Hair loss usually from the scalp. "In addition to changes in small and large intestines, loss of EPCAM results in hyperkeratosis in the skin and forestomach, hair follicle atrophy leading to alopecia, nephron hypoplasia in the kidney, proteinuria, and altered production of digestive enzymes by the pancreas." (PMID 35730316, 2022).
anaplastic cancer (1 paper, 2014). "Thus, a significantly higher expression of EpCAM and claudin-7 in the anaplastic cancer cell lines was confirmed at both the mRNA and protein levels." (PMID 24727741, 2014). "Our data suggest that expression of EpCAM may be upregulated in anaplastic cancer cells." (PMID 24727741, 2014).
benign kidney tumors (1 paper, 2021). "This phenotype was clearly distinct from that of the three benign kidney tumors (one cystic nephroma and two mesoblastic nephromas) studied, in which non-hematopoietic (benign) tumor cells were negative for both CD45 and CD56, while they co-expressed HLA-DR, CD10, and EpCAM." (PMID 34638431, 2021).
brain glioma (1 paper, 2015). A malignant glioma that involves the brain. "Our results showed that brain glioma cells, such as the cell line U118MG lack EpCAM expression, and cannot be isolated using the CellSearch platform." (PMID 25909322, 2015).
cardiac hypertrophy (1 paper, 2022). "Also, upon TGF-β1 stimulation, cardiac hypertrophy associated protein phospholipase C (PLC) and epithelial cell adhesion molecule (Ep-CAM), involved in epithelial-mesenchymal transition (EMT), showed a trend toward increased expression (p = 0.054 and p = 0.061, respectively)." (PMID 35360018, 2022).
celiac disease (1 paper, 2022). An autoimmune genetic disorder with an unknown pattern of inheritance that primarily affects the digestive tract. "Endothelial-derived (CD31+) and epithelial-derived (EpCAM+) EV counts were significantly lower in subjects under gluten exclusion than in celiac disease patients, although EpCAM+ EVs maintained higher counts than healthy subjects." (PMID 36615729, 2022). "Interestingly, EpCAM+ EV counts were significantly different between celiac disease patients undergoing gluten-exclusion diets and healthy controls, possibly suggesting that EpCAM+ EVs are markers of mucosal damage." (PMID 36615729, 2022). "Our data show that newly diagnosed celiac disease patients show higher numbers of circulating EVs than age- and sex-matched healthy subjects, owing in part to the increase in the endothelial- (CD31+), platelet- (CD41a+), epithelial-(EpCAM+), and leukocyte-derived (CD45+) EVs." (PMID 36615729, 2022).
cholangitis (1 paper, 2009). An acute or chronic inflammatory process affecting the biliary tract. "As the epithelium of the biliary system typically expresses the EpCAM-antigen, this side effect could be presumably attributed to a transient trAb-induced cholangitis." (PMID 19216794, 2009).
chronic hepatitis B (1 paper, 2016). "In patients with chronic hepatitis B, EpCAM is up-regulated." (PMID 26984381, 2016).
chronic hepatitis C (1 paper, 2015). "During liver injury (chronic hepatitis C/B), EpCAM marks those hepatocytes, freshly derived from stem cells, but is lacking on those derived from pre-existing hepatocytes, thus suggesting an association of EpCAM with multipotent progenitors." (PMID 25477371, 2015).
colorectal polyps (1 paper, 2020). "A complete loss of EPCAM expression was observed in two colorectal polyps, while in the other five, the staining was lost only in isolated glands." (PMID 33003511, 2020). "Of the 43 lesions from patients with EPCAM deletions, 17 (17/43; 39.5%) cases were informatively EPCAM-negative: 7 colorectal polyps and 10 CRC." (PMID 33003511, 2020).
corneal amyloidosis (1 paper, 2013). "Although speculative in nature, it is conceivable that regulated intramembrane proteolysis of Trop2, which was described recently in detail, results in the generation of Aβ-like fragments similarly to EpCAM and contributes to corneal amyloidosis." (PMID 24009667, 2013).
cutaneous squamous cell carcinoma (1 paper, 2021). "However, EpCAM may be upregulated in a tumor arising from epithelium that normally lacks expression of the protein, such as cutaneous squamous cell carcinomas in humans." (PMID 33614766, 2021).
Depression (1 paper, 2025). "The literature mining analysis revealed that BHLHE41 and GSTM2 have been previously implicated in both Depression and BC pathogenesis, while EPCAM has been primarily associated with BC." (PMID 40508038, 2025). "Furthermore, the study uncovers that EpCAM, a gene previously linked to BC progression, may also contribute to the pathogenesis of depression, addressing a critical gap in this field." (PMID 40508038, 2025). "Overall, BHLHE41, EPCAM, and GSTM2 consistently suggested their potential as reliable mechanism-associated genes for Depression and BC, with AUC values exceeding 0.7 across both training and validation datasets." (PMID 40508038, 2025). "Additional analyses identified consistent negative correlations between BHLHE41 and activated dendritic cells (for Depression: p < 0.05; for BC: p < 0.01), EpCAM and immature B cells (for Depression: p < 0.05; for BC: p < 0.01), and GSTM2 and γδ T cells (p < 0.05) across both datasets." (PMID 40508038, 2025). "In the Depression-GSE76826 dataset, the area under the curve (AUC) values were BHLHE41 (0.8333), EPCAM (0.7500), ADH4 (0.7500), GSTM2 (0.8333), and GADD45G (0.8500)." (PMID 40508038, 2025). "Least absolute shrinkage and selection operator (LASSO) regression identified five candidate genes (BHLHE41, EPCAM, ADH4, GSTM2, GADD45G) from the Depression and BC datasets." (PMID 40508038, 2025). "In the Depression-GSE169459 validation set, the AUC values were BHLHE41 (0.8667), EPCAM (0.8667), ADH4 (0.5333), GSTM2 (0.9333), and GADD45G (0.8667)." (PMID 40508038, 2025). "Although the existing literature has not established a direct correlation between EpCAM and Depression, emerging evidence suggests that EpCAM may contribute to depressive pathogenesis through multiple neuroinflammatory pathways." (PMID 40508038, 2025).
diabetes (1 paper, 2021). "The protein profiles at baseline were attenuated during guideline-based diabetes treatment and several plasma proteins associated with metformin medication independently of metabolic variables, such as circulating EPCAM." (PMID 33279861, 2021).
diarrhoea (1 paper, 2017). "Expansion of apical membrane and ectopic appearance of the brush border at TCs in EpCAM-mutated cells explain chronic intestinal absorption incapacity and pathological diarrhoea in CTE patients." (PMID 28084299, 2017).
duodenal carcinoma (1 paper, 2020). "Among our eleven patients with EPCAM deletions in exon 9, only one presented a duodenal carcinoma, while the remainder corresponded to CRC, corroborating these findings." (PMID 33003511, 2020).
duodenal tumor (1 paper, 2019). "Notably, one duodenal tumor was also recorded, confirming a previous suggestion of increased risk, but the data are insufficient for correlating this clinical phenotype to particular EPCAM genotypes." (PMID 30916491, 2019).
dysplasia (1 paper, 2016). A usually neoplastic transformation of the cell, associated with altered architectural tissue patterns. "The increased expression of EpExMem and Ep-ICDNuc in dysplasia in comparison with normal tissues suggests an overall upregulation of EpCAM expression as well as its increased proteolysis that would account for increased Ep-ICDNuc." (PMID 27421772, 2016).
enterovirus infection (1 paper, 2020). "Therefore, further studies are required to gain more comprehensive knowledge about the possible role of EpCAM in EV-mediated transmission of enterovirus infection among beta cells." (PMID 33171580, 2020).
experimental autoimmune encephalomyelitis (1 paper, 2022). An autoimmune demyelinating disease of the central nervous system that is produced experimentally in animals by the injection of homogenized brain or spinal cord in Freund's adjuvant. "In previous work, despite reduced numbers of CD207+EPCAM+ migratory DCs detected in the DLNs of ACKR2-/- mice at day 3 post immunization with antigen, deficiency of ACKR2 did not impair T-cell priming and subsequent development of experimental autoimmune encephalomyelitis." (PMID 36518752, 2022).
Failure to thrive (1 paper, 2020). Failure to thrive (FTT) refers to a child whose physical growth is substantially below the norm. "Expression of mTROP2 or hEpCAM in the IEC of EpCAM knockout mice prevented CTE that is routinely manifested by diarrhea, failure to thrive, and neonatal demise." (PMID 32781650, 2020).
Fulminant hepatic failure (1 paper, 2015). Hepatic failure refers to the inability of the liver to perform its normal synthetic and metabolic functions, which can result in coagulopathy and alteration in the mental status of a previously healthy individual. "Our data are further corroborated in human fulminant hepatic failure, in which, upon 80% loss of hepatocyte compartment, huge numbers of proliferating EpCAM+ biliary epithelial cells are observed." (PMID 25533785, 2015).
gastric cardia carcinoma (1 paper, 2025). A carcinoma that arises from epithelial cells of the cardia of stomach. "For instance, CD24+CD44+EpCAM+ gastric CSCs are significantly associated with poor patient prognosis, and the NNMT+/AQP5+ phenotype could serve as a potential diagnostic marker for gastric cardia cancer." (PMID 40665579, 2025).
H1N1 virus infection (1 paper, 2022). "As expected, we observed that 5-MF administration could reverse the elevated frequency of EpCAM colocalized with TUNEL and active caspase 3 elicited by H1N1 virus infection." (PMID 36180831, 2022).
Hyperkeratosis (1 paper, 2022). Hyperkeratosis is a histopathological term defining a thickened stratum corneum and may be present in many different skin conditions, with many possible overlaps. "Interestingly, hyperkeratosis was also observed in the forestomach, implying that a possible role of EPCAM in the terminal differentiation of keratinized epithelia (D′, arrowheads)." (PMID 35730316, 2022).
ichthyosis (1 paper, 2020). Disorders of cornification that are characterized by visible scaling and/or hyperkeratosis of most or all of the skin. "Neither EpCAM nor TROP2 cleavage was promoted by protease-disabled matriptase or matriptase that harbored the ichthyosis-associated G827R mutation." (PMID 32326212, 2020).
infectious diarrhea (1 paper, 2015). "It will also be of interest to study the impact of decreased EpCAM on the expression of absorptive transporters in the murine model as a possible explanation for fluid loss, as has been reported in some models of infectious diarrhea." (PMID 25482158, 2015).
insulinomas (1 paper, 2012). "Interestingly, EpCAM is known to be upregulated during islet development and in many tumor types including insulinomas, suggesting that T cell responses against autoantigens induced during islet regeneration may be significant markers for disease progression." (PMID 22253836, 2012).
intestinal polyp (1 paper, 2023). Discrete abnormal tissue masses that protrude into the lumen of the intestine. "To identify Il22ra2-expressing cells in the intestine, we purified EpCAM+ epithelial cells and CD45+ leukocytes from intestinal polyps and found that Il22ra2 mRNA was expressed only in CD45+ but not in epithelial cells." (PMID 36932082, 2023).
leukocytosis (1 paper, 2025). "Moreover, while we observed that markers such as EPCAM and ERBB2 were downregulated in CRC, further research is required to clarify the impact of inflammatory responses, such as leukocytosis, on the detectability of circulating RNA in patients with CRC." (PMID 40003943, 2025).
lobular breast cancer (1 paper, 2012). "For this reason, particular attention should be given to clinical studies determining the efficacy of EpCAM-targeting agents in the subgroup of patients with lobular breast cancer." (PMID 23110550, 2012). "However, EpCAM expression is usually low in lobular breast cancer as compared to ductal cancer, and the phenotype of lobular breast cancer resembles that of cancer cells undergoing EMT described in the present study." (PMID 23110550, 2012). "Considering our data on an anti-tumorigenic effect of EpCAM in mesenchyme-like cancer cells, targeting EpCAM in patients with lobular breast cancer might even result in a counterproductive effect." (PMID 23110550, 2012).
malaria (1 paper, 2023). Malaria is a serious and sometimes fatal disease caused by a parasite that commonly infects a certain type of mosquito which feeds on humans. "In this section, we compare the binding ability of the malaria protein and EpCAM to different types of tumor cells." (PMID 37569448, 2023). "Previous results have confirmed that the malaria protein is a broader-spectrum tumor marker than EpCAM." (PMID 37569448, 2023). "Further, we verified the binding strength of the malaria protein and EpCAM to these two cells by flow cytometry." (PMID 37569448, 2023). "Therefore, malaria proteins are advantageous over EpCAM as surface markers to capture CTCs." (PMID 37569448, 2023).
malignant pleural mesothelioma (1 paper, 2021). A malignant neoplasm that arises from mesothelial cells in the pleura and shows a diffuse growth pattern. "However, as CellSearch is an epithelial cell adhesion molecule (EpCAM)-dependent cell-capture system, it fails to identify CTCs in non-epithelial tumors with low EpCAM expression, such as malignant pleural mesothelioma (MPM)." (PMID 34025789, 2021).
mucoepidermoid carcinoma (1 paper, 2023). A carcinoma morphologically characterized the presence of cuboidal mucous cells, goblet-like mucous cells, squamoid cells, cystic changes, and a fibrotic stromal formation. "For example, in our study, in mucoepidermoid carcinoma, all cases with poor differentiation (100%) showed strong expression of EpCAM (p < 0.001)." (PMID 37627911, 2023).
neuroblastic tumor (1 paper, 2021). A group of nervous system tumors which display neuronal differentiation. "Thus, among neuroblastic tumors, i) CD90, GD2, CD9, and CD56 were the most discriminative between NBL and GNB, whereas ii) CD271, EpCAM, CD9, and CD81 discriminated NBL from PHEO." (PMID 34638431, 2021).
oropharyngeal squamous cell carcinoma (1 paper, 2021). "Similarly, the polyclonal R&D EpCAM antibody showed substantial variability in capturing the SCCF-3 feline oropharyngeal squamous cell carcinoma cell line under static conditions." (PMID 33614766, 2021). "We tested two anti-human EpCAM antibodies, designated for use with flow cytometry, for detection of surface EpCAM expression on feline cell lines derived from normal mammary and renal epithelia and mammary and oropharyngeal squamous cell carcinomas in cats." (PMID 33614766, 2021). "Positive staining was seen with the goat polyclonal R&D EpCAM antibody on the feline normal and neoplastic mammary cell lines and the oropharyngeal squamous cell carcinoma cell lines, whereas no staining was evident on the NLFK normal renal epithelial cell line." (PMID 33614766, 2021).